CD34 (CD34 molecule)
Diseases named in the same sentence as CD34 in open-access papers (continued):
Sharing a sentence is not in itself a finding about the gene and the disease.
tumor (continued). "Immunohistochemically, the tumor cells stained positively for vimentin, desmin, CD34, ER, and PgR and negatively for S-100, EMA, CK19, CD99, HMB45, and α-smooth muscle actin." (PMID 28831707, 2017). "In this case, the immunohistochemical findings were compatible with SFT, as the tumor cells were positive for CD34 and bcl-2, whereas alpha-SMA, desmin, and S-100 were negative." (PMID 28063145, 2017). "Hypoxic microenvironment was exhibited in tumor frozen slides stained for pimonidazole, Hoechst 33342, hematoxylin-eosin and CD34." (PMID 28969036, 2017). "To characterize the microvasculature of the KPIC tumor, we stained the microvasculature with CD34 antibodies and found that microvessels rarely branched, and basal microvilli grew on these vessels, as observed in human PC." (PMID 28475592, 2017). "Blood vessels feeding the tumor were identified by means of CD34 and Endoglin (CD-105) expression, demonstrating strong positivity for CD34 in all the endothelial cells, whereas CD 105 marked a smaller number of blood vessels." (PMID 28390134, 2017). "Immunohistochemically, the tumor cells stained positively for CD34, estrogen receptor (ER), and progesterone receptor (PgR) and negatively for S-100, EMA, CK19, CD99, HMB45, and α-smooth muscle actin." (PMID 28831707, 2017). "The characteristics of hypoxia (pimonidazole), tumor blood perfusion (Hoechst 33342), microvessel formation (CD34) and morphology [hematoxylin-eosin (HE)] of tumors were examined and compared in 0 Gy, 10 Gy and 20 Gy pre-irradiated mice." (PMID 28969036, 2017). "Using IF, we analyzed the co-localization of PDPN-positive CAFs with blood vessels stained with antibody directed against CD34 in tumor stroma of IDC samples." (PMID 28938000, 2017). "On immunohistochemical examination, the tumor cells were positive for alpha-smooth muscle actin, desmin, CD34 and h-caldesmon." (PMID 28214470, 2017). "To clarify this point and to avoid a misinterpretation, we classified the tumours according to the expression of the endothelial marker CD34 in order to discard those tumours with high angiogenesis and vessels content from the analysis." (PMID 27966446, 2017). "Evidence for a tumour-initiating cell or ‘cancer stem cell’ (CSC) was first provided by Bonnet and Dick in acute myeloid leukemia where it was shown that the CD34 + /CD38- subset of cells exhibits high tumour-initiating efficiency in mice." (PMID 28904399, 2017). "Discrete VEGFR2+ and CD34+ tumor vessels were manually scored in invasive ductal, lobular, mixed ductal-lobular and colloid (N = 139, 22, 18, 7) BRC cores." (PMID 28533703, 2017). "On immunohistochemical (IHC) examination, the sarcoma tumor cells were stained positive for CD34, CD31, vimentin, CD68, Calponin, F8 and Ki67 (80%), while negative for Bcl-2, Desmin, EMA, SMA, CK and ALK-1." (PMID 29113426, 2017). "For each case, immunohistochemical expression of VEGFR2 protein was evaluated in the tumor vasculature outlined by vascular endothelial immunoreactivity for CD34." (PMID 28533703, 2017). "The intravascular growth pattern of the tumor cells was highlighted by CD34 staining of the endothelial cells." (PMID 28841887, 2017). "Tumor tissues with CD34-positive microvessels were observed by immunohistochemistry, and the tumor microvessel densities were calculated." (PMID 29162156, 2017). "In conclusion, our results showed that 5-FU-loaded nanobubbles irradiated with low-frequency ultrasound can significantly reduce the level of CD34 expression in transplanted HCC tumor tissues." (PMID 29162156, 2017). "We confirmed in newly-diagnosed M4/5 subtype AML patients that there were increased levels of pro-inflammatory cytokines TNF and IL-1 in their peripheral blood, which correlated to the increased TNF and IL1 expression by CD34+ tumor cells." (PMID 28039479, 2017). "Eighty-nine of 186 (48%) cases had >10 CD34+ tumor vessels, while 97/186 (52%) had fewer CD34+ vessels in each TMA core." (PMID 28533703, 2017).
tumor (continued). "Immunohistochemical staining revealed that tumours derived from sFRP1-overexpressing cells contained more proliferative cells (assayed by Ki-67 staining) and more microvessels (assayed by CD34 staining)." (PMID 28169332, 2017). "The results illustrated that reduced Ki67-positive cells, CD31-positive cells and CD34-positive cells were found in miR-193a-overexpressed xenograft tumor cells." (PMID 29141691, 2017). "Immunohistochemically, the tumor cells were positive for CD34, bcl-2 and STAT6, whereas alpha-SMA, desmin, and S-100 were negative." (PMID 28063145, 2017). "Immunohistochemical staining of the biopsy specimen using the c-kit antibody displayed diffuse cytoplasmic staining, and the tumor cells were positive for CD34 expression." (PMID 28421549, 2017). "We were able to genetically mark the engrafted CD34+ bone marrow cells as well as the tumor cells, and follow the endogenous leukocytic infiltration into the autologous tumor." (PMID 28008146, 2017). "CD34 expression was positive in the abundant normal hepatic sinusoid (black asterisks) and tumor angiogenesis (black arrows and arrow heads)." (PMID 28122521, 2017). "NS-G mice were inoculated with a mixture of either HeLa or MDA-MB-435 cells and s4428z- or CD34-transduced T lymphocytes (at E:T of 1:1), and we measured tumor development in the following weeks." (PMID 29085357, 2017). "In non-tumor control cells (CD34+HSC and CD133+HSC), all studied polyphenols when used in combination with each of the three antimetabolite agents antagonized their effects significantly increasing ATP levels and cell survival (P≤0.05)." (PMID 29285220, 2017). "In confirmation of this, staining for CK7 and CD34 in spontaneous MDA‐MB‐231LM2–4 lung metastases demonstrated that these tumours have an alveolar HGP and that they do co‐opt alveolar capillaries." (PMID 27859259, 2017). "Immunohistopathological evaluation of explanted HT-29 tumor specimen demonstrated an increased intratumoral neoangiogenesis induction in tumors (CD 31, CD34) as well as an increased tumor cell VEGF expression compared to normal liver tissue." (PMID 28475639, 2017). "Second, using immunofluorescence, the co-localization of PDPN-positive CAFs with blood vessels stained with antibody directed against CD34 was observed in tumor stroma of IDC samples." (PMID 28938000, 2017). "The number of microvessels with CD34-positive staining was decreased in group D, and the tumor MVD was significantly lower than that of the other groups (P < 0.05)." (PMID 29162156, 2017). "CD34 staining revealed that AG488 treatment significantly decreased microvessel density in tumor tissue samples from the untreated group (p<0.05)." (PMID 29069750, 2017). "In some cases, regions of striking CD34 expression by neoplastic cells abruptly gave way to areas in which tumor cells of identical histological appearance were entirely CD34-nonreactive." (PMID 27812792, 2017). "DFSP is a rare cutaneous soft tissue sarcoma with distinct histologic features, including a storiform pattern of growth, spindle-shaped tumor cells, and CD34-positive staining." (PMID 28977029, 2017). "All ten cases studied also manifested both intense and often widespread tumor cell expression of CD34 as well as the presence in regional cortex of ramified, CD34-expressing neural elements in large numbers." (PMID 27812792, 2017). "Haemangiopericytoma, solitary fibrous tumour, giant cell angiofibroma, and fibrous histiocytoma are all CD34+ fibroblastic tumours with similar features." (PMID 28449640, 2017). "Vimentin and CD34 are related to tumor growth, invasion, and metastasis; however, Ki67 protein is a marker of tumor cell proliferation." (PMID 28358024, 2017).
tumor (continued). "Histologic and immunohistochemical study of the breast nodule revealed the presence of a breast mesenchymal tumor with the same characteristics as the scalp nodule, and the result was positive for CD34." (PMID 28388964, 2017). "Here, we report on a case of IVC tumor positive for c-kit and CD34 expression which was considered EGIST." (PMID 28421549, 2017). "These tumours originate from the mesenchyme and are consistently immunoreactive for CD34 with benign to uncertain behaviour." (PMID 28449640, 2017). "In our study, VEGF, VEGFR, and CD34 expression was strongly suppressed after treatment, indicating that the blood supply of tumours was inhibited." (PMID 28054548, 2017). "Currently, MVD, which can be quantified by the specific marker CD34 for vascular endothelial cells, has been widely used to estimate the degree of tumor angiogenesis." (PMID 28404940, 2017). "By means of CD34 co-expression, the level of PSMA expression in tumor associated neovasculature was investigated." (PMID 29077706, 2017). "In the untreated tumor model, the tumor center had greater CD34 microvessel density compared to the tumor rim." (PMID 28456115, 2017). "To confirm the anti-angiogenic effect of HCaRG in experimental RCCs, we performed immunohistochemical staining of tumor microvessels using anti-CD34-antibody." (PMID 29050225, 2017). "For CD31 and CD34, the microvessel endothelium was highlighted in both the tumor and in normal liver sinusoids." (PMID 28475639, 2017). "From auto-radiography study, high concentration of CD34 staining was found in the periphery of tumor, and lower level of staining appeared in the tumor center, consistent with auto-radiography images." (PMID 29088775, 2017). "CD34, a marker related to dedifferentiation of tumor cell, has a favorable effect in differential diagnosis between HGDNs and WD-SHCCs." (PMID 29152084, 2017). "Of note, Gab2 enhanced tumorigenesis and tumor growth in mouse xenografts with high Ki67 expression, and led to an increased vessel density with strong CD34 and VEGFR2 activity." (PMID 28420432, 2017). "Immunohistochemical staining demonstrated that tumor cells were positive for c-kit and CD34 expression." (PMID 28421549, 2017). "The trans-differentiation of tumor cells into endothelial-like cells, which were CD45− CD31+ CD34+ (termed tumor-derived endothelial cells, TDECs) and GSCs that were CD133+CD144+ initiated and promoted VM in GBM models." (PMID 29258180, 2017). "Since we showed that human BMC-derived cells from CD34+ grafts indeed reconstituted the murine thymic stroma, we reasoned that these T cells should be tolerant to the HLA-A2+ transplanted tumor that is seen in human tumor." (PMID 28008146, 2017). "Immunohistochemical analyses of Oct4A KD tumor xenografts demonstrated a significant loss of cytokeratin 7 (CK7), Glut-1 as well as CD34 and CD31 compared to vector control cell-derived xenografts." (PMID 27390927, 2016). "In contrast, it has been established earlier that CD34+ quiescent stem cells in the bulge are targets for transformation into tumor-initiating cells in chemocarcinogenesis." (PMID 27409834, 2016). "Immunohistochemistry was used to detect the protein expression levels of vimentin, CD34, Ki-67 and E-cadherin in transplanted tumor tissues." (PMID 26871290, 2016). "Compared with placebo, the number of CD34 positive microvessels in subcutaneous tumours decreased by 81% following administration of anakinra via the treatment protocol (P < 0.01) and by 94% following the preventative protocol (P < 0.001)." (PMID 27765923, 2016). "Rather, our results show that endocan expression in tumor cells more accurately reflects the invasiveness when compared to that of CD34/CD105-positive MVDs." (PMID 26809958, 2016). "A similar staining pattern was also seen with SOX2 for cells within the tumor nests (red) and the stroma (red), and the endothelium marked by CD34 (green)." (PMID 27532037, 2016).
tumor (continued). "Tumor cells are CD34, CD99, and bcl2 positive, while the S-100 protein, actin, and desmin are negative." (PMID 27579199, 2016). "Immunohistochemistry was used to detect the expression of HIF-1a and the vascular specific marker CD34, and tumor growth curves were drawn." (PMID 27456341, 2016). "In the meantime, we found IL-37-over-expressing tumors had decreased CD34 level, which suggested an inhibited tumor angiogenesis." (PMID 26791086, 2016). "CD34 is a myeloid stem-cell marker and is thought to play an important role in maintaining stromal integrity and inhibiting tumor cell migration." (PMID 26762320, 2016). "These human-specific CD34-positive vessels were observed inside the tumor mass, while vessels immediately underneath the capsule from surrounding mouse tissue were positive for mouse-specific CD34." (PMID 27382431, 2016). "The dynamics of CD34 and αSMA expression in tumour stroma infiltrated by ASCs has been previously reported as an indicator of cancer aggressiveness." (PMID 27241286, 2016). "Immunohistological analyses of tumor demonstrated a reduction in tumor angiogenesis (CD34), in proliferative activity (KI-67) and an increase in apoptosis (tunnel) in tumors treated with N6L compared with control tumors." (PMID 26993766, 2016). "The results of the in vitro cell migration and destruction of VM channels as well as in vivo cell apoptosis and CD34-PAS dual staining confirmed the anti-tumor and anti-VM activity of NGR-SSL-CA4 in vitro and in vivo." (PMID 27283987, 2016). "Pearson’s rank correlation testing demonstrated a significant, albeit weak, correlation between CD34/CD105-MVDs and endocan expression in tumor cells (CD34: P = 0.034, Pearson’s r = 0.262; CD105: P < 0.010, Pearson’s r = 0.316)." (PMID 26809958, 2016). "Thus, the loss of CD-34 staining in SFT of the kidney may promote tumor metastasis to other organs." (PMID 27239363, 2016). "In our case, the tumour cells showed negativity with CD34 but stromal cells showed diffuse positivity." (PMID 27034895, 2016). "The use of CD34 for the prognosis, diagnosis, and treatment of neoplasms has been increasingly discussed." (PMID 26886640, 2016). "The associations between endocan expression, CD34/CD105-positive microvessel densities (MVDs), and Knosp tumor invasion grades were evaluated." (PMID 26809958, 2016). "In both tumor-bearing mouse models, the numbers of leukocytes, erythrocytes, reticulocytes and platelets as well as the percentage of CD34+ cells were elevated remarkably in combined therapy of SEP and 5-FU groups compared to 5-FU-treated group." (PMID 27385218, 2016). "NANOG was expressed by cells within the tumor nests (red) and the stroma (red), as well as the endothelium of the microvessels that stained positively for CD34 (green)." (PMID 27532037, 2016). "Antiangiogenic effect was further evaluated by tumor microvessel density (MVD) using IHC staining of CD34." (PMID 26872471, 2016). "Immunohistochemistry revealed CD10 positivity in the tumour cells and strong CD34 expression in the stromal cells." (PMID 27034895, 2016). "In this study, we developed a hu-mouse model that permits efficient generation of tumor antigen-specific human T cells from genetically engineered CD34+ cells." (PMID 26824989, 2016). "In order to investigate the effect on tumor microvessels, endothelial cells lining endothelial microvessels (EM) were detected by staining with an anti-CD34 monoclonal antibody." (PMID 27669225, 2016). "In order to investigate the distribution of FANP at the tumor sites in depth, the tumor sections were stained with CD34 antibody and FR antibody." (PMID 27273770, 2016). "TUNEL assays and immunohistochemical staining of Ki-67 and CD34 were used to assess apoptosis, cell proliferation, and angiogenesis in all tumor cell samples." (PMID 27750216, 2016).
tumor (continued). "Inhibition effect on microvessel density represented by CD31 and CD34 in PC-3 and LNCaP xenograft tumor tissue of quercetin and 2-ME was further investigated by immunohistochemistry." (PMID 26011145, 2015). "This study suggests that saw palmetto extract can effectively reduce the expression of CD34 in tumor cells, so that it can effectively inhibit the tumor angiogenesis." (PMID 26788112, 2015). "This was accomplished by immunostaining tissue samples collected out of all three tumor zones from each patient individually using specific antibodies against Map2 and CD34." (PMID 25609379, 2015). "The CD34− tumor cells were then cultured in suspension cultures to form tumor spheres with or without TAMs, at a ratio of 1:50 (TAM: tumor cell), reflecting the normal abundance of TAMs within the tumors." (PMID 25762633, 2015). "Statistically significant positive correlations were found between the densities of peripheral tumor CD34+ blood vessels and peritumoral D2-40+ lymphatic vessels (p = 0.01)." (PMID 25652007, 2015). "In contrast, for vascular endothelial cells in the tumor tissues, CD34 was found to be positively expressed." (PMID 26303928, 2015). "Confirmation of these findings was performed by immunostaining of tumor sections with an antibody against CD34, an endothelial cell marker, followed by quantification of the CD34-positive area or CD34-positive number." (PMID 26284361, 2015). "The percentage of Ki67-positive cells and the numbers of CD34 positive vascular structures in tumor xenografts were reduced by Ci, Ci/Mi, and EH/Ci/Mi treatments relative to PBS controls." (PMID 26088171, 2015). "Immunohistochemically, the tumor revealed strong and diffuse staining for CD34, bcl-2, and vimentin, and a high mitotic index (seven mitoses per 10 high-power fields)." (PMID 25649645, 2015). "Tumor MVD stained with CD34 positively correlated with nPE (r = 0.637, P <0.001), nWiAUC (r = 0.604, P <0.001), nWiR(r = 0.633, P < 0.001), and nWiPI (r = 0.602, P <0.001)." (PMID 25884471, 2015). "The efficacy of VM channel elimination was evaluated using the periodic acid-Schiff (PAS)-CD34 dual staining assay, and the VM channels were stained in red in the tumor slices." (PMID 26429872, 2015). "At this time we tested a cryopreserved sample of the batch of tumor-primed NK cells he had received for their ability to inhibit in vitro myelopoiesis by the HLA-matched sibling CD34+ cells in colony forming assays." (PMID 26062124, 2015). "Previous studies have confirmed that tumor markers, including CD34+, Bcl-2+ and CD99+, are generally positive in SFT cases, which has aided the diagnosis of SFTs." (PMID 25452776, 2015). "Positive staining for CD34 was observed in tumor core blood vessels, peritumoral vessels, and in blood vessels associated with normal breast tissue." (PMID 25652007, 2015). "EHE tumours are detected by positive immunostaining for endothelial cell markers, including CD31, CD34 and factor VIII-associated antigen." (PMID 25663869, 2015). "HF bulge markers CD34, K15 and NFATc1 were decreased in tumours isolated from both K14ΔNLef1 and K15ΔNLef1 animals when compared with DMBA-treated skin of wild-type mice." (PMID 25608467, 2015). "CD34 is expressed in the endothelial cells of micro-vessels that migrate during angiogenesis, and CD34 was used to assess vascularity in the tumor samples." (PMID 26013572, 2015). "To determine the role of BMDCs in tumor development, we stained the tumor slices with an antibody targeting CD34, a vascular endothelial precursor cell marker." (PMID 26416452, 2015). "Cixutumumab-treated tumours of STAT3 shRNA-transfected MDA231–Luc cells showed significant decreases in levels of IGF-2 expression, F4/80+ macrophages (left) and CD34+ VE cells (right) when compared with control tumours." (PMID 26465273, 2015).